CNOT6L (CCR4-NOT transcription complex subunit 6 like)
Description:
Has 3'-5' poly(A) exoribonuclease activity for synthetic poly(A) RNA substrate. Catalytic component of the CCR4-NOT complex which is one of the major cellular mRNA deadenylases and is linked to various cellular processes including bulk mRNA degradation, miRNA-mediated repression, translational repression during translational initiation and general transcription regulation. Additional complex functions may be a consequence of its influence on mRNA expression. May be involved in the deadenylation-dependent degradation of mRNAs through the 3'-UTR AU-rich element-mediated mechanism. Involved in deadenylation-dependent degradation of CDKN1B mRNA. Its mRNA deadenylase activity can be inhibited by TOB1. Mediates cell proliferation and cell survival and prevents cellular senescence.
Synonyms: CCR4B; DKFZp434K098
Tractability: Small molecule: a structure with a bound ligand is known. PROTAC: ubiquitination databases record sites on it; its protein half-life has been measured.
Target class: Enzyme; Hydrolase
Gene: Protein-coding gene on chromosome 4 (77,713,387 to 77,819,615, reverse strand). Ensembl gene ENSG00000138767.
Subcellular location: Cytoplasm; Nucleus
Subcellular location (Human Protein Atlas): Cytosol
Pathways (Reactome):
Developmental Biology: M-decay: degradation of maternal mRNAs by maternally stored factors
Metabolism of RNA: Deadenylation of mRNA
Gene Ontology:
Molecular function: poly(A)-specific ribonuclease activity; protein binding; 3'-5'-RNA exonuclease activity; catalytic activity
Biological process: positive regulation of cell population proliferation; positive regulation of cytoplasmic mRNA processing body assembly; nuclear-transcribed mRNA poly(A) tail shortening
Cellular component: CCR4-NOT complex; cytoplasm; cytosol; nucleus
Genetic constraint (gnomAD): Loss-of-function variants: 3 observed, 45.91 expected, observed/expected ratio (o/e) 0.0653, 90% interval 0.029 to 0.17. The upper end of that interval is the gene's LOEUF score, 0.17, which puts it in group 1 of 6, group 1 being the genes least tolerant of losing a copy. Missense variants: 184 observed, 548.63 expected, observed/expected ratio (o/e) 0.34, 90% interval 0.3 to 0.38. Synonymous variants: 160 observed, 202.04 expected, observed/expected ratio (o/e) 0.79, 90% interval 0.69 to 0.9.
Homologues: Orthologues: chimpanzee CNOT6L (99% identical), macaque CNOT6L (99% identical), rabbit CNOT6L (99% identical), dog CNOT6L (99% identical), rat Cnot6l (98% identical), mouse Cnot6l (97% identical), pig CNOT6L (94% identical), tropical clawed frog cnot6l (90% identical), zebrafish cnot6l (83% identical), guinea pig CNOT6L (83% identical), Drosophila melanogaster twin (58% identical), Caenorhabditis elegans ccr-4 (42% identical), and 2 more. Paralogues in human: CNOT6 (79% identical), PDE12 (22% identical), NOCT (19% identical), ANGEL2 (19% identical), ANGEL1 (19% identical).
Diseases named in the same sentence as CNOT6L in open-access papers:
CNOT6L is named in the same sentence as 26 diseases in open-access papers, as found by Europe PMC text mining. Sharing a sentence is not in itself a finding about the gene and the disease. The quoted sentences say what the papers report.
breast carcinoma (4 papers, 2015 to 2023). "Indeed, high expression of NFATC3, CBX6 and CNOT6L is associated with better survival in breast cancer patients." (PMID 37409119, 2023). "The knockdown of CNOT6 and/or CNOT6L reduced cell proliferation and cell survival, while gene expression profiling reveals that the enzymes regulate distinct gene sets associated with breast cancer cell proliferation, apoptosis, and the inhibition of tumor development." (PMID 35630580, 2022). "The model implemented by SPINNAKER predicted a total of 99,662 sponge interactions, with 4223 associated to breast cancer and 2 of them experimentally confirmed in breast cancer (CNOT6L-PTEN and ZEB2-PTEN)." (PMID 35524174, 2022). "To extend the previous analysis, we included data from silencing of CNOT6, CNOT6L, CNOT7, and CNOT8 from another cell line, namely, MCF7 (derived from pleural effusion of breast carcinoma), based on previous studies." (PMID 35630580, 2022).
type 2 diabetes (2 papers, 2024 to 2025). "We found that the core genes (CNOT6L and GRIN2B) are associated with type 2 diabetes, diabetic complications, dyslipidemia, hyperglycemia, and inflammation." (PMID 39433858, 2024). "WB and RT-qPCR results showed that in different pathways, CNOT6L protein and mRNA levels were upregulated in type 2 diabetes." (PMID 39433858, 2024). "Elevated expression of CNOT6L is notably observed in type 2 diabetes, where it contributes to diabetic complications, inflammation, and other physiological processes through the regulation of miRNA and related signaling pathways, ultimately resulting in a poor prognosis." (PMID 40458121, 2025). "CNOT6L can be used as a potential therapeutic target for type 2 diabetes." (PMID 39433858, 2024). "Consequently, CNOT6L may represent a potential therapeutic target for type 2 diabetes." (PMID 40458121, 2025).
acute myeloid leukemia (1 paper, 2014). Acute myeloid leukemia (AML) is a group of neoplasms arising from precursor cells committed to the myeloid cell-line differentiation. "The expression of CNOT6L and CNOT7 was reportedly down-regulated in samples of leukemia cells taken from ALL and AML (acute myeloid leukemia) patients compared to normal blood cells, while the expression of CNOT6 was slightly up-regulated." (PMID 25191340, 2014).
bladder cancer (1 paper, 2024). "FASN, MAP2 and BMP6 were highly expressed in bladder cancer, while GPC2, CNOT6L, GALNT12 and CARD10 were expressed at low levels in bladder cancer." (PMID 38218866, 2024).
colon adenocarcinoma (1 paper, 2024). "The function of CNOT6L has not been elucidated; however, one previous study demonstrated a significant copy number loss of CNOT6L in human colon adenocarcinoma samples." (PMID 39251997, 2024).
colorectal cancer (1 paper, 2023). A primary or metastatic malignant neoplasm that affects the colon or rectum. "NEDD4, CNOT6L, and DNA repair protein RAD51 homolog 2 (RAD51B) were previously associated with IBD, tuberculosis, and colorectal cancer, respectively." (PMID 37512987, 2023).
leukemia (1 paper, 2024). A malignant (clonal) hematologic disorder, involving hematopoietic stem cells and characterized by the presence of primitive or atypical myeloid or lymphoid cells in the bone marrow and the blood. "The expression of CNOT6L was reportedly downregulated in samples of leukemia cells from patients with acute lymphoblastic and myeloid leukemia compared to that in normal blood cells." (PMID 39251997, 2024).
polycystic ovary syndrome (1 paper, 2025). A disorder that manifests as multiple cysts on the ovaries. "The findings provide novel insights into the role of CNOT6L in regulating energy metabolism homeostasis and its involvement in follicular developmental disorders associated with polycystic ovary syndrome." (PMID 40458121, 2025). "This study offers new insights into the role of CNOT6L in regulating energy metabolism homeostasis and its involvement in follicular developmental disorders related to polycystic ovary syndrome." (PMID 40458121, 2025). "This implies that the excessive activation of CNOT6L in granulosa cells, induced by various factors, may mediate metabolic disturbances through the process of deadenylation and could be associated with the disordered follicle development observed in polycystic ovary syndrome." (PMID 40458121, 2025). "In this study, we detect the expression level of the deadenylase CNOT6L in polycystic ovarian syndrome (PCOS) patients’ granulosa cells and mouse models’ ovaries." (PMID 40458121, 2025). "Drawing upon previous research findings, we propose the hypothesis that variations in the levels of the deadenylase enzyme CNOT6L in ovarian granulosa cells may influence follicular developmental dysfunction in polycystic ovary syndrome by modulating energy metabolism pathways." (PMID 40458121, 2025). "By re-analyzing previously reported sequencing data of ovarian granulosa cells in polycystic ovary syndrome, which were GSE138518, GSE155489, and GSE173160, we identified a significant increase in CNOT6L mRNA expression levels in the ovarian granulosa cells of individuals with PCOS." (PMID 40458121, 2025).
prostate carcinoma (1 paper, 2017). A carcinoma that arises from epithelial cells of the prostate gland. "To ascertain whether the crosstalk between TNRC6B and CNOT6L was PTEN-dependent, we repeated the experiment in the prostate cancer cell line PC3, which is PTEN-null." (PMID 28798471, 2017).
type 2 diabetes mellitus (1 paper, 2024). A type of diabetes mellitus that is characterized by insulin resistance or desensitization and increased blood glucose levels. "The results of this study indicate that the core genes (CNOT6L and GRIN2B) are associated with diabetes, T2D, diabetic complications, abnormal blood lipids, high blood sugar, and inflammation." (PMID 39433858, 2024).
tumor (4 papers, 2016 to 2023). "This indicates, that high levels of NT5E promoting miRNAs such as miR-224 or low expression of NT5E repressor such as CBX6/CNOT6L or NFACT3 are linked to progressive tumor disease reflected by shorter survival time." (PMID 37409119, 2023). "Overall, siRNA-mediated knockdown of CBX6, CNOT6L, and SRSF4 consistently enhanced NT5E surface levels in various human tumor cell lines." (PMID 37409119, 2023). "For instance, it has been shown that the expression of the tumor-suppressor gene PTEN can be regulated by its miRNA-mediated competitors VAPA, CNOT6L, SERINC1 or ZNF460." (PMID 26812364, 2016). "Further investigations of the RNA binding proteins that recruit transcripts for deadenylation and studies into possible roles of the other CCR4-NOT deadenylase subunits Cnot6 and Cnot6l in metastatic progression may reveal additional important insights into tumor autonomous metastatic mechanisms." (PMID 26807845, 2016).
cancer (2 papers, 2022 to 2025). A tumor composed of atypical neoplastic, often pleomorphic cells that invade other tissues. "The depletion of CNOT6L in cancer MCF7 cells and mouse NIH3T3 cells impairs cell proliferation, but highlights differences in the expression of specific genes assuming cell type-specific roles for the CNOT6 and CNOT6L." (PMID 35630580, 2022). "Regarding the levels of deadenylases in cancer, it is shown that in acute types of leukemia (AML, ALL), the levels of both PARN and CNOT6 increase compared to non-malignant clinical samples, while the opposite is the case for CNOT6L and CNOT7." (PMID 35630580, 2022). "Although we demonstrate that antiproliferative activity of RNF219 is at least partially mediated by regulation of CNOT6L expression, further investigation would be required to conclude that the impact of RNF219 activity on cancer progression is mediated by the CCR4‐NOT complex." (PMID 40598799, 2025).
cardiovascular disease (1 paper, 2023). "To date, no human diseases have been associated with Cnot6l nor is its genetic influence on cardiovascular disease known." (PMID 37221250, 2023).
heart disease (1 paper, 2023). "Although one (Gatb) has already been linked to heart disease in the literature, the other three phenotypes (Cnot6l, Slc6a15, Sytl4) describe novel findings worth further exploration." (PMID 37221250, 2023).
metabolic disorders (1 paper, 2025). "The activity of CNOT6/CNOT6L is modulated by various stimulus, such as nutrient levels, highlighting its involvement in metabolic regulation and potential links to metabolic diseases." (PMID 40837873, 2025). "The study provides valuable insights into the posttranscriptional regulation of GDF15 by CNOT6L and highlights the potential of targeting this pathway for the treatment of metabolic disorders." (PMID 40837873, 2025).
CNOT6L also shares sentences with these, for which no sentence is quoted: B cell lymphomas (1 paper); dyslipidemia (1); female infertility (1); Hyperglycemia (1); infertile (1); lymphoma (1); male infertility (1); myeloid leukemia (1); Pleural effusion (1); rectum cancer (1); tuberculosis (1).